RNASE1 (ribonuclease A family member 1, pancreatic)
Description:
Endonuclease that catalyzes the cleavage of RNA on the 3' side of pyrimidine nucleotides. Acts on single-stranded and double-stranded RNA.
Synonyms: RIB1; RNS1; RAC1
Tractability: Antibody: UniProt places it where antibodies can reach, with medium confidence; UniProt predicts a signal peptide or a membrane-spanning region; its Gene Ontology location is reachable by antibodies, with medium confidence. PROTAC: a small molecule that binds it is known.
Target class: Enzyme
Gene: Protein-coding gene on chromosome 14 (20,801,228 to 20,802,884, reverse strand). Ensembl gene ENSG00000129538.
Subcellular location: Secreted
Subcellular location (Human Protein Atlas): Vesicles; Nucleoplasm; Predicted to be secreted
Pathways (Reactome):
Autophagy: Chaperone Mediated Autophagy; Late endosomal microautophagy
Developmental Biology: Developmental Lineage of Pancreatic Acinar Cells
Gene Ontology:
Molecular function: protein binding; RNA nuclease activity; ribonuclease A activity; nucleic acid binding
Biological process: defense response to virus; defense response to Gram-positive bacterium
Cellular component: extracellular exosome; extracellular region
Genetic constraint (gnomAD): Loss-of-function variants: 1 observed, 0.74 expected, observed/expected ratio (o/e) 1.35, 90% interval 0.3 to 1.91. That is too few expected variants to judge how well the gene tolerates losing a copy. Missense variants: 203 observed, 210.56 expected, observed/expected ratio (o/e) 0.96, 90% interval 0.86 to 1.08. Synonymous variants: 64 observed, 82.92 expected, observed/expected ratio (o/e) 0.77, 90% interval 0.63 to 0.95.
Homologues: Orthologues: chimpanzee RNASE1 (98% identical), macaque RNASE1 (87% identical), pig RNASE1 (75% identical), guinea pig RAC1 (67% identical), mouse Rnase1 (67% identical), rat Rnase1 (65% identical), dog RAC1 (64% identical), rabbit RNASE1 (62% identical), rat Rnase1l2 (61% identical), rat Rnase1l1 (59% identical). Paralogues in human: RNASE4 (44% identical), RNASE8 (35% identical), RNASE7 (35% identical), RNASE2 (31% identical), RNASE6 (31% identical), ANG (29% identical), RNASE3 (29% identical), RNASE10 (27% identical), RNASE13 (21% identical), RNASE9 (21% identical), RNASE12 (20% identical), RNASE11 (19% identical).
Diseases named in the same sentence as RNASE1 in open-access papers:
RNASE1 is named in the same sentence as 106 diseases in open-access papers, as found by Europe PMC text mining. Sharing a sentence is not in itself a finding about the gene and the disease. The quoted sentences say what the papers report.
breast cancer (14 papers, 2014 to 2025). A primary or metastatic malignant neoplasm involving the breast. "In this study, our risk model based on TIPARP, SAMD4A, TSEN54, GSPT2, and RNASE1 was compared with the high and low risk groups of breast cancer cell lines in the CellMiner database." (PMID 36911389, 2023). "Notably, a study has found RNase1 might activate CD4+ T cells to inhibit breast cancer growth, while another has indicated it causes immunosuppression in liver cancer." (PMID 39932384, 2025). "For instance, RNase1 has been shown to interact with EphA4 in breast cancer, RNase5 with EGFR in pancreatic cancer, RNase4 with AXL in prostate cancer, RNase7 with ROS1 in liver cancer, respectively." (PMID 40246819, 2025). "Augmenting antitumor immunity by RNase1 addition represents a promising therapeutic strategy against breast cancer." (PMID 37416781, 2023). "Here, we established a syngeneic immunocompetent mouse model in breast cancer and demonstrated that ectopic RNase1 expression significantly inhibited tumor progression." (PMID 37416781, 2023). "Our results uncover a tumor-suppressive role of RNase1 through adaptive immune response in breast cancer in vivo and in vitro, providing a potential treatment strategy of combining RNase1 with cancer immunotherapies for immunocompetent patients." (PMID 37416781, 2023). "Studies in breast cancer showed that secretory RNase1 binds to and activates EphA4 signaling and the RNase1-EphA4-activating axis promotes stem cell-like properties and tumor growth in nude mouse models." (PMID 37416781, 2023). "Given that EphA4 serves as a cognate receptor of RNase1 in breast cancer, furthering our understanding of EphA4 on T cells is worth pursuing to expand the development of cancer treatments by targeting the RNase1-EphA4 axis in the immune system." (PMID 37416781, 2023). "To further validate the contribution of the RNase 1–EphA4 axis to breast tumorigenicity, we established mouse 4T1 mammary tumor cells, which harbored low endogenous mouse RNase 1 (mRNase 1), stably expressing mRNase 1 and vector control." (PMID 33986289, 2021). "Subsequently, we established E0771 breast cancer cells expressing mouse RNase1 (mR1) and a variant lacking ribonucleolytic activity (mR1‐H12A) and inoculated them into either immunocompetent or immune‐deficient NOD SCID mice." (PMID 39932384, 2025). "Our previous study found that RNase1 is a ligand of EPHA4 in breast cancer cells." (PMID 40246819, 2025). "In one HNSC (MOC‐L1, a mouse oral carcinoma cell line) and three breast cancer (4T1, E0771, and EMT6) mouse cell lines, MOC‐L1 and 4T1 cells expressed higher mRNA levels of RNase1 than E0771 and EMT6 cells." (PMID 39932384, 2025). "We next examined the impact of RNase1 on cancer growth and T‐cell activity in vivo by using syngeneic mouse models of HNSC and breast cancer." (PMID 39932384, 2025). "Consistent with the trend of results from public databases, TSEN54 was upregulated in breast cancer cell lines and GSPT2, RNASE1, SAMD4A, and TIPARP were downregulated in breast cancer cell lines." (PMID 36911389, 2023). "For breast cancer, we find out that HSPA2A, RNASE1, CLIC6, and IFITM1 are highly expressed in some specific groups." (PMID 33133130, 2020). "Notably, analysis of cancer-killing potential revealed that T cell-mediated antitumor immunity was enhanced by RNase1, which further collaborated with an EGFR-CD3 bispecific antibody to protect against breast cancer cells across molecular subtypes." (PMID 37416781, 2023). "For breast cancer, we select five essential genes, such as CTSA, HSPA2, RNASE1, CLIC6, IFITM1." (PMID 33133130, 2020). "Furthermore, we demonstrated that RNase1 increased the expression of immune inhibitory checkpoint proteins and compromised CD8+ T‐cell cytotoxicity in vitro, and in vivo experiments demonstrated that RNase1 inhibited CD8+ T‐cell activity, thereby promoting breast cancer growth." (PMID 39932384, 2025).
breast cancer (continued). "Next, to define whether the dysfunction of CD4+ and CD8+ T cells by RNase1 requires its ribonucleolytic activity, we expressed RNase1 (R1) and a catalytically inactive RNase1 mutant (R1‐H12A)[6b] in the low‐endogenous RNase1 expressing MDA‐MB‐231 breast cancer cells." (PMID 39932384, 2025).
gastric cancer (11 papers, 2014 to 2026). A primary or metastatic malignant neoplasm involving the stomach. "In gastric cancer, RNASE1 acted as a tumor suppressor gene, as its expression was demonstrated to decrease progressively from the normal, primary cancer and metastatic cells." (PMID 34249481, 2021). "Yet another report shown that RNase 1 has changed its expression level by microarray and western blotting method during the gastric cancer development." (PMID 24805924, 2014). "However, the significance of RNASE1’s involvement in gastric cancer has not been duly acknowledged." (PMID 39044041, 2024).
melanoma (10 papers, 2012 to 2025). A malignant, usually aggressive tumor composed of atypical, neoplastic melanocytes. "Recently obtained data revealed that RI-resistant variants of pancreatic RNase 1 of human displayed strong toxic effect toward lung cancer and melanoma cells and worked sinergically with protein kinases in the ERK pathway." (PMID 31572192, 2019). "Beyond polyamines, RNases can be complexed also with differently sized PEG moieties: indeed, a RNase 1 PEG-derivative is known to inhibit tumor growth in mice, while PEG-conjugated RNase A oligomers are cytotoxic against transplanted melanoma in mice as well." (PMID 31849926, 2019).
Sepsis (8 papers, 2016 to 2024). Sepsis is defined as life-threatening organ dysfunction caused by a dysregulated host response to infection. "Thereby, our data provides new insights in the regulation of sepsis-induced vascular dysfunction and offers novel treatment options to prevent sepsis-associated RNase1 repression and consecutive vascular breakdown." (PMID 37189117, 2023). "To this end, we investigated the impact of bEVs from sepsis-associated pathogens on RNase1 regulation in human lung microvascular ECs (HULEC-5a) as a model system." (PMID 37189117, 2023). "Here, we investigated the impact of bEVs from different sepsis-associated bacterial pathogens on the regulation of the vessel-protective factor RNase1 and the underlying signaling cascades in human lung ECs." (PMID 37189117, 2023). "Future investigation into RNase1 in the context of (pneumogenic) sepsis is crucial, as pneumonia is the leading cause of sepsis." (PMID 37189117, 2023). "Altogether, the current literature suggests a causal interaction between sepsis-associated EC dysfunction and RNase1 repression that is still insufficiently studied." (PMID 37189117, 2023). "Thereby, Ruxolitinib could be suitable to prevent sepsis-associated IL-6 release to impede EC dysfunction via promoting RNase1 expression." (PMID 37189117, 2023). "Besides that, studies in mice suggest that RNase1 administration can prevent sepsis-associated tissue and organ damage, highlighting its potential as a therapeutic intervention." (PMID 37189117, 2023). "Furthermore, our study suggests potential therapeutic strategies for sepsis-associated vascular dysfunction by restoring RNase1 function and vascular homeostasis." (PMID 37189117, 2023). "Besides these data, recent studies also investigated the role of the RNase1-eRNA system in sepsis suggesting a potential RNase1 repression during disease progression as well as a protective function of RNase1 during sepsis-associated tissue- and organ damage." (PMID 37189117, 2023). "However, massive and persistent inflammatory conditions frequently result in RNase1 repression, often being associated with vascular pathologies including sepsis progression." (PMID 39697663, 2021). "Starting from sepsis diagnosis, we measured significantly increased RNase 1 concentrations at all time points compared to healthy volunteers (all p < 0.0001)." (PMID 38951571, 2024). "PB treatment fully recovered RNase1 mRNA and protein and has been shown to reduce the proapoptotic function of plasma of septic patients in sepsis-induced acute renal failure." (PMID 37189117, 2023). "Although insufficiently studied in bacterial infections and sepsis, RNase1 administration has been shown to block the eRNA-mediated mechanism of alveolar epithelial cell infection by Streptococcus pneumoniae." (PMID 37189117, 2023). "RNase1 attenuated septic cardiomyopathy and cardiac apoptosis in a murine model of polymicrobial sepsis." (PMID 35388024, 2022). "Katrin reported about the impact of bacterial EVs and secreted host factors on the function of endothelial Ribonuclease 1 (RNase1) in sepsis." (PMID 39697663, 2021). "In conclusion, RNase 1, 3 and 7 are secreted into serum under conditions with tissue injury, such as major surgery or sepsis." (PMID 26927088, 2016). "RNase 1 and 3 were elevated in Sepsis compared to Surgery (2.2- and 3.1-fold, respectively; both p < 0.0001) or compared to Healthy (3.0- and 15.5-fold, respectively; both p < 0.0001)." (PMID 26927088, 2016). "We evaluated serum levels of RNase 1, 3 and 7 in 20 surgical sepsis patients (Sepsis), nine surgical patients (Surgery) and 10 healthy controls (Healthy)." (PMID 26927088, 2016). "Additionally, RNase1 levels are elevated in serum in the early disease stage of sepsis and can act as a prognostic factor for the development of multi-organ failure." (PMID 37189117, 2023).
Sepsis (continued). "However, sepsis progression leads to an increase in serum levels of RNase1 antagonists, eRNA and RNase-Inhibitor, potentially repressing RNase1." (PMID 37189117, 2023). "As IL-6 is also known as a key inflammatory mediator during cytokine storm in sepsis, further investigation of a possible impact of Ruxolitinib, JAK1 and IL-6 in RNase1-associated EC dysfunction might be of future interest." (PMID 37189117, 2023). "In summary, we observed that EVs released by different gram-negative, (pneumogenic) sepsis-associated bacteria repress RNase1, a key modulator of vascular integrity, in human lung microvascular ECs." (PMID 37189117, 2023). "Here, we investigated the impact of bEVs of sepsis-related pathogens on human EC RNase1 regulation." (PMID 37189117, 2023). "She reported that applied OMVs from sepsis sepsis-inducing bacteria in contrast to non-sepsis sepsis-inducing bacteria significantly reduced the activity of RNase1 and promoted endothelial cell activation, as indicated by increased IL-8, CXCL10, ICAM-1, and IL-1β expression." (PMID 39697663, 2021). "Thus, the aim of our study was to investigate serum levels of RNase 1, 3 and 7 to verify the secretion of RNAses in response to acute systemic infection such as sepsis in surgical patients." (PMID 26927088, 2016). "Blood stream bEVs from gram-negative, sepsis-associated bacteria reduce the vascular protective factor RNase1, opening new avenues for therapeutical intervention of EC dysfunction via promotion of RNase1 integrity." (PMID 37189117, 2023). "Additionally, new innovations such as PB-releasing nanoparticles have been developed to target bacterial accumulation and vascular inflammation and thereby could be a valuable tool for sepsis intervention through RNase1 recovery in human ECs." (PMID 37189117, 2023). "In recent years, the RNase1-eRNA system was identified as crucial factor in diverse pathologies, ranging from cardiovascular diseases, such as thrombosis, atherosclerosis or myocardial infarction, to inflammatory and infectious disorders like sepsis or bacterial infections." (PMID 33178683, 2020). "ICU patients with SARS-CoV-2 infection (Cohort A), grouped into increasing and decreasing RNase 1 serum levels, were evaluated for various biomarkers and scores (lactate, IL-6, PCT, CRP, sepsis-related organ failure assessment (SOFA) score, and Horowitz score) over a 14-day period." (PMID 37569802, 2023). "On the basis of these findings, RNase 1 and RNH1 serum levels may have the potential to predict post-operative sepsis, and thus the length of a hospital stay." (PMID 33066382, 2020). "Furthermore, sepsis patients with renal dysfunction were found to have significantly higher RNase 1 levels than patients without renal dysfunction." (PMID 37569802, 2023).
pancreatic cancer (7 papers, 2014 to 2025). "Besides the described ability to act as an anti-cancer drug, RNase1 is also suggested to operate as a tumor marker for pancreatic cancer, since tumor cells and cancer-associated ECs secreted a differently glycosylated form of RNase1 compared to healthy cells." (PMID 33015070, 2020). "Most downregulated RBPs include PAIP2B, SIDT2, PDCD4, AZGP1, and RNASE1, among which we report for the first-time involvement of PAIP2B, SIDT2, PDCD4, and RNASE1 in pancreatic cancer." (PMID 34912796, 2021). "Interestingly, we observed that there are reports of mutations and copy number variation in PAIP2B, PRDX1, RNASE1, BARD1, UHMK1, and RPL3L genes associated with pancreatic cancer." (PMID 34912796, 2021).
viral infection (7 papers, 2018 to 2023). "RNase 1 is a small endogenous antimicrobial polypeptide that possesses antiviral activity against viral diseases." (PMID 37569802, 2023). "Whether the application of RNase1 in this scenario may help to limit the extent of viral infections like COVID-19 and impact on leukocyte recruitment and emigration steps in immune defense in order to limit the extent of associated cardiovascular diseases remains to be studied." (PMID 33392206, 2020).
atherosclerosis (5 papers, 2020 to 2024). A disease characterized by the build-up of fatty material and calcium deposition in the arterial wall resulting in partial or complete occlusion of the arterial lumen. "RNase1 is a vessel-protective factor that counteracts the effects of eRNA, whose downregulation is linked to various vascular pathologies, like thrombosis, myocardial infarction, atherosclerosis and stroke." (PMID 37189117, 2023). "Interestingly, the findings suggest that RNASE1 may be a potential key gene implicated in the involvement of macrophages in the pathogenesis of atherosclerosis." (PMID 39364414, 2024). "Our findings highlight RNASE1’s integral role in atherosclerosis progression, implicating the gene in low-density lipoprotein (LDL), high-density lipoprotein (HDL), and cholesterol metabolism." (PMID 39364414, 2024). "Collectively, these findings underscore the pivotal role of RNASE1 in atherosclerosis development, implicating this gene in LDL, HDL, and cholesterol metabolism." (PMID 39364414, 2024). "Yet, to elucidate the detailed molecular mechanisms behind RNASE1’s impact on macrophage function in atherosclerosis, further experimental inquiry is crucial." (PMID 39364414, 2024). "Ultimately, a Venn diagram pinpointed CD14 and RNASE1 as the distinctive characteristic genes for atherosclerosis, derived from the intersected findings of the three modeling techniques." (PMID 39364414, 2024). "Inhibition of RNASE1 in an atherosclerosis macrophage cell line resulted in decreased total cholesterol (TC) and lactate dehydrogenase (LDH) release." (PMID 39364414, 2024). "Furthermore, the potential of RNASE1 as a therapeutic target has been unveiled, enhancing the current understanding and opening avenues for pioneering treatment strategies for atherosclerosis." (PMID 39364414, 2024). "The study also demonstrated that hsa_circ_0004104 may contribute to the pathogenesis of CAD by upregulating of atherosclerosis-susceptible genes, such as IDO1, MMP8, CD40, and downregulating of anti-atherosclerosis genes, such as ApoA I, RNASE1." (PMID 33421993, 2021).